XRCC2 (X-ray repair cross complementing 2)
Diseases named in the same sentence as XRCC2 in open-access papers (continued):
Sharing a sentence is not in itself a finding about the gene and the disease.
non-small cell lung carcinoma (1 paper, 2017). A group of at least three distinct histological types of lung cancer, including non-small cell squamous cell carcinoma, adenocarcinoma, and large cell carcinoma. "Herein, we took advantage of TCGA data, screening candidate DNA-repair genes (RAD51B, RAD51C, RAD51D, XRCC2, and XRCC3) with covariance and correlation matrices in mRNA level from complete 1124 complete cases of non-small cell lung cancer clinical data." (PMID 29207658, 2017).
osteosarcoma (1 paper, 2019). A usually aggressive malignant bone-forming mesenchymal neoplasm, predominantly affecting adolescents and young adults. "Given that CHO cells deficient for RAD51C, RAD51D, XRCC2 or XRCC3, and human HCT116 cells deficient for XRCC3 are viable, we attempted to disrupt each classical RAD51 paralog individually in transformed human osteosarcoma U2OS and human embryonic kidney HEK293 cells." (PMID 31584931, 2019).
psychological distress (1 paper, 2019). "The consequences of assigning a high-risk status to a woman based on an XRCC2 mutation are non-trivial and may lead to increased psychological distress and possibly to unwarranted preventive surgery." (PMID 31463769, 2019).
pterygium (1 paper, 2021). A wedge-shaped fibrovascular lesion arising from the bulbar conjunctiva and extending to the cornea. "It was previously reported that genes involved in double-strand DNA break repair, RAD50, RAD51, XRCC2 and XRCC3, are differentially expressed in pterygium." (PMID 34769520, 2021).
schwannoma (1 paper, 2020). A benign, usually encapsulated slow growing tumor composed of Schwann cells. "XRCC2 and MLL3/KMT2C were involved in homologous recombination repair and histone modification, suggesting that loss of DNA damage repair and epigenetic alterations might also play key roles in schwannoma." (PMID 33193598, 2020).
skin toxicity (1 paper, 2025). "Similarly, RAD51C, like XRCC2, is vital for HR, and polymorphisms that diminish its activity can reduce repair fidelity and heighten acute skin toxicity." (PMID 40507362, 2025).
T-cell lymphoma (1 paper, 2016). "Similarly, inhibition of Pim kinase in T-cell lymphoma cells downregulated genes involved in DNA repair, including XRCC2 (HR), XRCC5 (encoding Ku80, in the NHEJ pathway), and ERCC8 (nucleotide excision repair)." (PMID 27374090, 2016).
cancer (63 papers, 2009 to 2026). A tumor composed of atypical neoplastic, often pleomorphic cells that invade other tissues. "Pathogenic variants of ATM (ataxia-telangiectasia mutated), CHEK2 (checkpoint kinase 2), PALB2 (partner and localizer of BRCA2), and XRCC2 (X-ray repair cross-complementing 2) tumor suppressor genes (TSGs) have been associated with the development of cancers." (PMID 38784039, 2024). "Polymorphisms in XRCC2 are associated with the development of various cancers, including lung, gastric, cervical, colon, breast, and others." (PMID 37679817, 2023). "The X-ray repair complementing defective repair in Chinese hamster cells 2 gene (XRCC2) codes for a DNA repair protein, and XRCC2 expression in some cancers is associated with increased radioresistance." (PMID 35643812, 2022). "We also identified other deletions associated with higher HRD in multiple cancer types, such as XRCC2/3 and BARD1 deletion in BLCA, TP53BP1, and RAD51 deletion in OV and LUAD, and CHEK1 deletion in TCGT and SKCM, etc.." (PMID 34572800, 2021). "In exon 3, an Arg188His polymorphism (rs3218536) has been identified on the coding region of XRCC2 as potential cancer susceptibility loci in recent studies, although association results are controversial." (PMID 34319046, 2021). "XRCC2, a homologous recombination-related gene, has been reported to be associated with a variety of cancers." (PMID 34051735, 2021). "An association between XRCC2 (rs3218536) single-nucleotide polymorphisms (SNPs) and cancer incidence risk are found to be the most common mutation observed by numerous studies." (PMID 32458654, 2020). "It has also been well characterized that mutations in XRCC2 are often associated with numerous types of cancers, strongly suggesting that XRCC2 is probably involved in tumorigenesis by regulating HR repair." (PMID 29549248, 2018). "Common genetic variants in XRCC2, particularly a coding SNP in exon 3 (R188H, dbSNP ID rs3218536), have been identified as potential cancer susceptibility loci recently, though the association results were controversial." (PMID 29038438, 2017). "Conversely, XRCC2-deficient cancer cells were more sensitive to irradiation in vitro, and a higher proportion of these cells underwent cell death induced by G2/M phase arrest and apoptosis." (PMID 26320178, 2015). "Association between the single nucleotide polymorphism rs3218536 (known as Arg188His) located in the X-ray repair cross complementing group 2 (XRCC2) gene and cancer susceptibility has been widely investigated." (PMID 24621646, 2014). "The XRCC2 Arg188His polymorphism was widely reported to be associated with susceptibility of a wide range of cancers." (PMID 24621646, 2014). "Numerous studies have reported an association between XRCC2 SNPs and the cancer incidence risk; the most common mutation studied being the XRCC2 rs3218536 SNP." (PMID 25120693, 2014). "PubMed and Embase databases were searched systematically until September 7, 2013 to obtain all the records evaluating the association between the XRCC2 Arg188His polymorphism and the risk of all types of cancers." (PMID 24621646, 2014). "Mutations in XRCC2 compromise the DNA repair mechanisms and increase susceptibility to cancers." (PMID 38784039, 2024). "XRCC2 (X-ray repair cross-complementing) is another gene with cancer predisposition." (PMID 38784039, 2024). "XRCC2 is a homologous recombination‐related gene implicated in a variety of cancers." (PMID 39540204, 2024). "XRCC2 gene polymorphisms can potentially lead to alterations in the primary structure of XRCC2 or abnormal protein expression, resulting in impaired repair of DNA damage and increased susceptibility to cancer." (PMID 37679817, 2023). "The increment of cancer risk is appeared due to two known epigenetic causes of XRCC2 deficiency." (PMID 32458654, 2020). "The majority of earlier studies on cancer susceptibility have focused only on XRCC2 rs3218536 SNP." (PMID 29038438, 2017).
cancer (continued). "Theoretically, genetic variants in the XRCC2 gene could change the regular function of this gene, disturb the DNA repair and increase cancer risk." (PMID 24621646, 2014). "In conclusion, our meta-analysis found that the impact of the XRCC2 Arg188His polymorphism on susceptibility of different cancers might be diverse." (PMID 24621646, 2014). "Current evidence indicated that the XRCC2 Arg188His polymorphism might play various roles in different cancer types." (PMID 24621646, 2014). "Stratified analysis of the XRCC2 Arg188His polymorphism on cancer susceptibility." (PMID 24621646, 2014). "Given the essential role of XRCC2 gene in tumorigenesis, and a relatively small sample size for a single study, we conducted a meta-analysis including all published literature to evaluate the impact of the XRCC2 Arg188His polymorphism on susceptibility of all available types of cancer." (PMID 24621646, 2014). "Both Pcna and Xrcc2 have also been implicated in DNA repair deficits in certain cancers." (PMID 24002865, 2013). "Therefore, we examined LARC patients, in vitro models of CRC, and an in vivo model of CRC in which the tumors had different XRCC2 status to assess the radiosensitizing effect of olaparib, a drug approved for the treatment of several cancers with BRCA mutations." (PMID 35643812, 2022). "Furthermore, SNPs of XRCC2 may also increase the risk of several types of cancer including thyroid, brain and breast cancer." (PMID 29038438, 2017). "Particularly, the Arg194Trp and Arg399Gln variants of XRCC1, the Arg188His variant of XRCC2, and the Thr241Met variant of XRCC3 have been studied for their associations with various types of cancer." (PMID 38983993, 2024). "X-ray repair cross complementing group 2(XRCC2)gene, located in 7q36.1, is an essential part of the homologous recombination repair pathway and a functional candidate for involvement in cancer progression." (PMID 36761956, 2023). "It seems possible that when cancer cells lose XRCC2 function, they develop an alternative or compensatory pathway(s) for DNA repair." (PMID 35643812, 2022). "Studies have reported that XRCC2 affects the efficacy of cancers and participates in the malignant progression of different tumors." (PMID 34051735, 2021). "In our literature search, we found studies showing that lower XRCC2 in cancer cells increases temozolomide efficacy by inhibiting their ability to repair the DNA damage induced by temozolomide." (PMID 33654134, 2021). "We analyzed the expression of XRCC2 in various cancers and their corresponding normal tissues using the GEPIA2 online platform." (PMID 34051735, 2021). "In this study, based on the GEPIA2 analysis, we found that the expression level of XRCC2 in various cancers, including GBM, was significantly higher than that in the corresponding normal tissues." (PMID 34051735, 2021). "XRCC2 is a DNA repair gene that has been found to play an essential role in the development of many cancers." (PMID 34051735, 2021). "In order to clarify the expression pattern of XRCC2 in cancer and its impact on prognosis, we chose GBM as the research object for follow-up study." (PMID 34051735, 2021). "In case of Australian population, a comparative consequence of the XRCC2 alteration to cancer threat is remarked for members of this family." (PMID 32458654, 2020). "XRCC1 and XRCC2 are involved in the BER and HR pathways, respectively, and have been associated with the occurrence of cancer." (PMID 32684929, 2020).
cancer (continued). "Similar to XRCC1 and XRCC2, XRCC3 has been researched widely in the correlation between gene polymorphisms and the risk of cancer." (PMID 32258128, 2020). "XRCC2 Arg188His and XRCC3 Thr241Met polymorphisms were selected for their documented participation in the pathogenesis of cancers." (PMID 30712190, 2019). "We found that XRCC2 expression is upregulated in nearly all types of cancers, to a degree comparable to RAD51 while much higher than RAD51C." (PMID 29549248, 2018). "Consistent with the data mining result, the average of relative mRNA level of XRCC2 is 5.2-fold higher in cancer cells than that in normal cells." (PMID 29549248, 2018). "To develop the methods of a XRCC2 promoter-based cancer diagnosis and treatment, we first created a lentiviral vector bearing pXRCC2-luciferase based on the FUGW lentiviral vector." (PMID 29549248, 2018). "In vitro studies on the 2101 bp XRCC2 promoter demonstrate that its activity is ~6190-fold higher in cancer cells than in normal cells according to a luciferase reporter assay." (PMID 29549248, 2018). "Statistical analysis reveals that XRCC2 is significantly higher at mRNA level in cancer cells than that in normal cells, indicating that the XRCC2 promoter is potentially cancer specific." (PMID 29549248, 2018). "The construct comprised of the XRCC2 promoter driving expression of diphtheria toxin A (pXRCC2-DTA) selectively kills cancer cells while having only a very mild effect on normal cells." (PMID 29549248, 2018). "We further confirmed the upregulation of XRCC2 in cancer cells by comparing the XRCC2 mRNA levels between a collection of cancer cells and normal cells." (PMID 29549248, 2018). "Consistent with the data above, we found that the XRCC2 promoter is significantly hyperactivated in the group of cancer cells." (PMID 29549248, 2018). "On average, the XRCC2 promoter activity in cancer cells is ~950-fold higher than that in normal cells." (PMID 29549248, 2018). "Here, we focused on the human RAD51 paralogs—RAD51B, C, D, XRCC2, 3, and SWSAP1—and explored their known and emerging functions, the challenges in further uncovering their roles, and their association with cancer predisposition." (PMID 30551670, 2018). "Our data demonstrated that using lentivirus-mediated delivery of pXRCC2-DTA significantly suppressed the growth of tumors in vivo, strongly indicating that utilization of the XRCC2 promoter for cancer therapy with a viral delivery is extremely promising." (PMID 29549248, 2018). "Although the way of virus-mediated delivery needs to be further improved, our proof-of-concept study demonstrates the feasibility of using viral vehicles containing XRCC2 promoter for cancer diagnosis and treatment in various types of tumors in vivo." (PMID 29549248, 2018). "In present study five polymorphisms, present in different regions of XRCC2 gene, such as promoter region, exonic region and intronic region were screened in HNC cancer patients and controls." (PMID 29038438, 2017). "The polymorphisms of the XRCC2 and XRCC3 were investigated by PCR–RFLP in 70 patients with TNBC and 70 age- and sex-matched non-cancer controls." (PMID 24728564, 2015). "XRCC2 gene, located in 7q36.1, is an essential part of the homologous recombination repair pathway and a functional candidate for involvement in cancer progression." (PMID 25743260, 2015). "As research moved along, the genomic landscape of cancer has been gradually brought into light, and an increasing number of vital genes shared by various cancers, XRCC2 for example, have been revealed in recent years." (PMID 24621646, 2014). "According to this concept, restraining PARP1 could be a latent therapeutic schedule for the therapy of cancers with defects in precise DNA repair genes, such as XRCC2, MRE11, and BRCA1/2." (PMID 38907095, 2024). "Xrcc2’s involvement in the DNA damage pathway may also indicate a cancer-related outcome for the highest cmQTL related to Hoechst labeling distribution." (PMID 38662777, 2024).
cancer (continued). "Loss of XRCC2 compromises DNA damage repairs, and induced DNA damage burdens may increase the reliance on PARP-dependent DNA repairs of cancer cells to render cell susceptibility to PARP inhibitor therapy." (PMID 35643812, 2022). "Furthermore, in vivo studies using a viral vector containing XRCC2 promoter indicated that XRCC2 is a promising target for the diagnosis and treatment of various types of cancers." (PMID 34486486, 2021). "But the most remarkable pro-cancer RAD52 phenotype is seen in cancer cells deficient in any of the following DNA repair proteins: BRCA1, BRCA2, PALB2, XAB2 or RAD51 paralogs: RAD51B, RAD51C, RAD51D, XRCC2 and XRCC3." (PMID 34887904, 2021). "BIRC5 and XRCC2 regulate antiapoptosis and DNA repair, contributing to cancer chemoresistance." (PMID 34154613, 2021). "Based on this, the XRCC2 gene has been included in several clinical cancer genetic test panels." (PMID 31463769, 2019). "No cancer type was more common in first- or second-degree relatives of XRCC2 mutation carriers than in relatives of the non-carriers." (PMID 31463769, 2019). "In summary, the newly identified XRCC2 promoter and its utilization in the transcriptional targeting of cancer cells could achieve the major goals of cancer therapy: high selectivity and efficacy." (PMID 29549248, 2018). "The next steps would be modifying the lentiviral vector to completely eliminate the interference from other regulatory elements on the XRCC2 promoter, or switching to other viral vehicles such as adenovirus or adenovirus-associated virus (AAV) system in order to improve the cancer specificity." (PMID 29549248, 2018). "Nevertheless, using the SC HeLa xenograft model, we were still able to distinguish tumor tissues from normal tissues, strongly suggesting that the XRCC2 promoter could be a powerful tool for cancer diagnosis." (PMID 29549248, 2018). "We therefore set out to examine whether introduction of a vector containing the XRCC2 promoter driving DTA expression to cells may selectively eliminate cancer cells." (PMID 29549248, 2018). "Similar to RAD51 and RAD51C, the XRCC2 promoter is hyperactivated in the group of cancer cells." (PMID 29549248, 2018). "Although single nucleotide polymorphisms have been identified in these DNA repair genes, such as XRCC2, but the influence of specific genetic variants on repair phenotype and cancer risk has not yet been identified." (PMID 29038438, 2017). "XRCC2 has been shown to increase the radioresistance of some cancers." (PMID 26320178, 2015). "XRCC2 and XRCC3 genes involved in homologous recombination repair (HRR) of DNA and in the maintenance of the genome integrity play a crucial role in protecting against mutations that lead to cancer." (PMID 24728564, 2015). "No cancer type was more common in first- or second-degree relatives of XRCC2 mutation carriers than in relatives of the non-carriers—there were in total 20 cancers in 26 families with the XRCC2 mutation (77%) versus 8380 cancers in 11,672 XRCC2 mutation-negative families (72%)." (PMID 31463769, 2019). "XRCC2 Arg188His polymorphism was not related, either to tumor size or cancer type or grade." (PMID 24728564, 2015). "However, not all XRCC2-deficient cancer cells were sensitive to IR in vitro." (PMID 35643812, 2022). "Specifically, EGFR is a widely studied oncogene with a potential role in cancer therapeutics, six are core genes (AURKA, CDK1, CDT1, PRKDC, RAD51, and XRCC2), six are potential drug targets, and five were identified as drug actionable genes." (PMID 33240468, 2020). "The five classical RAD51 paralogs [RAD51B, RAD51C, RAD51D, XRCC2 and XRCC3] are important components of the homologous recombination pathway that preserves genomic integrity and protects against cancer." (PMID 31584931, 2019).